CCNB1 (cyclin B1)
Diseases named in the same sentence as CCNB1 in open-access papers (continued):
Sharing a sentence is not in itself a finding about the gene and the disease.
hepatocellular carcinoma (continued). "CCNB1 and BIRC5 have been reported to be related to the immune infiltration of hepatocellular carcinoma, and their expressions are positively correlated with the infiltration levels of CD4 + T cells and dendritic cells, respectively." (PMID 36175893, 2022). "AURKA, CDK1, CCNB1 and TOP2A were significantly upregulated and correlated with poor prognosis in hepatocellular carcinoma, AUC values of which were 95.7, 96.9, 98.1 and 96.1% respectively." (PMID 35078445, 2022). "Overexpression of CDK1, CCNB1 and CDC20 in tumor tissues predicted poor survival of patients with hepatocellular carcinoma." (PMID 34253236, 2021). "The cell cycle-related molecules CDK1 and CCNB1 are the most connected hub genes, and these genes have been reported to be potential diagnostic or prognostic markers in a variety of tumours, such as glioblastoma malignancies, hepatocellular carcinoma and non-muscle invasive bladder cancer." (PMID 31870357, 2019). "The expression of cell cycle-related protein (cyclin B1), invasion and metastasis-related proteins (MMP-7 and MMP-9) and Akt-related proteins in hepatoma cells was also decreased after knocking down KIF18A." (PMID 29466986, 2018). "CCNB1, CCNE2, and FOXM1 were three other genes that were differentially expressed in more than one carcinoma with survival implications, specifically in kidney clear cell and liver carcinoma." (PMID 37345032, 2023). "The modes of action of drug-molecule interactions that may be effective against hepatocellular carcinoma core genes CCNA2, CCNB1, and CDK1 were investigated." (PMID 36479313, 2022). "When we merged these hub genes with differentially expressed genes in GSE14520 dataset and differentially expressed genes of hepatocellular carcinoma in GEPIA database, seven communal genes were found, they were AURKA, CDK1, CCNB1, TOP2A, CYP3A4, CYP2C9, and CYP2B6." (PMID 35078445, 2022). "CDK2, CDK4, CCNB1 and CCND1 can accelerate the cell cycle moving from G1 to S phase and then promote the proliferation of various cell types including mouse embryonic fibroblasts, mouse neural progenitor cells and human hepatocellular carcinoma." (PMID 34438874, 2021). "Adopting a series of bioinformatics analysis methods, the current study identified 763 DEGs and seven hub genes (CDC20, CDK1, MAD2L1, BUB1, BUB1B, CCNB1, and CCNA2) that may be involved in hepatocellular carcinoma tumorigenesis and progression." (PMID 33767726, 2021). "The results showed that knocking down either HNF4α or Exo70 in human hepatoma cells reduced the expression of Cdc2, while had no influence on the expression of Cyclin B1 and Cdk7." (PMID 26848864, 2016). "Following the synthesis of CCNB1, CDC20, CDC7, BUB1B, and MCM3 have been examined in hepatocellular carcinoma (HCC) samples." (PMID 36497125, 2022).
lung cancer (93 papers, 2009 to 2025). A malignant neoplasm involving the lung. "CCNB1 was found to be associated with tumor aggressiveness and poor survival in lung cancer and esophageal cancer." (PMID 31844590, 2019). "In the stratified analysis by cancer types, cyclin B1 overexpression was associated with worse 3-year OS of lung cancer (OR = 2.95, 95% CI = 1.64 to 5.30, P = 0.0003), and esophageal cancer (OR = 4.95, 95% CI = 2.58 to 9.50, P < 0.00001)." (PMID 27903976, 2017). "Subgroup analysis revealed that elevated cyclin B1 expression was associated with worse prognosis of lung cancer and esophageal cancer but better prognosis of colorectal cancer." (PMID 27903976, 2017). "Increased CHK1/2 activity by Tax during S phase restricts the CDK-dependent phosphorylation of FOXM1, preventing the premature expression of G2/M genes, including those encoding cyclin-dependent kinase 4, cyclin B1, and cyclin A2, all common DEGs in lung cancer." (PMID 39228892, 2024). "Thus, SCCAg, CCNB1 and DNA repair genes estimation can be used as predictor biomarkers for early-staged lung cancer susceptibility in PAHs exposed workers." (PMID 36287252, 2023). "In summary, the present study reveals that elevated AKR1B10 enhances glycolysis through regulation of LDHA and the resulting elevated lactate promotes transcriptional activation of the cell cycle-related gene CCNB1 by histone lactylation, inhibiting the susceptibility of lung cancer BM cells to PEM." (PMID 37587486, 2023). "Knockdown of RING1 increased lung cancer cell proliferation and migration in vitro and in vivo, linked to the upregulation of CIP2A and its downstream molecules, c‐MYC and Cyclin B1." (PMID 41362702, 2025). "Further investigations have revealed that MEOX1 suppresses the progression of lung cancer cells by inhibiting the cell cycle checkpoint gene CCNB1." (PMID 38180753, 2024). "Our finding demonstrates that AKR1B10/glycolysis/H4K12la/CCNB1 promotes acquired PEM chemoresistance in lung cancer BM, providing novel strategies to sensitize PEM response in the treatment of lung cancer patients suffering from BM." (PMID 37587486, 2023). "The ROC curves demonstrated good diagnostic efficacy for lung cancer, with AUC values of 0.962, 0.924, 0.886, and 0.95 for the four hub genes CENPF, AURKA, PBK, and CCNB1, respectively." (PMID 36984548, 2023). "In consistence with previous report, TIM-4 overexpression promoted proliferating cell nuclear antigen (PCNA), Cyclin A2, Cyclin B1 expression in lung cancer cells." (PMID 36806050, 2023). "Other studies have demonstrated that CCNB1 participates in the lung cancer related lncRNA-miRNA-mRNA ceRNA network." (PMID 36339610, 2022). "CCNB1 was reported as one of the driver genes for lung cancer from the bioinformatic meta-analysis of gene expression data of non-small cell lung cancer with protein-protein interaction data." (PMID 36291764, 2022).
lung cancer (continued). "Recent studies have reported that AP is involved in cell cycle arrest at the G2/M phase via blockade of the cyclin B1/cdc2 complex and upregulation of p21 and p27 in lung cancer cells." (PMID 34760374, 2021). "Upon JMJD8 knockdown in lung cancer cell lines, cyclin B1, RhoA, RhoC, MMP9, and N-cadherin were down-regulated, and p21 and E-cadherin were conversely up-regulated." (PMID 33442397, 2021). "It has revealed cyclin B1 plays a facilitating role in various malignant tumor development 14, such as breast, colorectal, lung cancer and so on." (PMID 34131395, 2021). "Curcumin has shown to downregulate CCNB1 expression in PCa, colon and lung cancer which has been linked to G2/M arrest." (PMID 34366863, 2021). "Our study revealed that B. nigra extract altered the G2/M checkpoint regulator cyclin B1 and increased the G2/M cell cycle arrest in lung cancer cells." (PMID 32365503, 2020). "In lung cancer, hypoxia induces BRG1 to regulate the proliferation and migration of lung cancer cells by activating cyclin B1 and LTBP2, whereas loss of BRG1 via siRNA treatment decreases hypoxia-induced migration and proliferation." (PMID 32354028, 2020). "It was previously reported that treatment of human lung cancer cell line A549 with CT also resulted in downregulation of cyclin B1 and G2/M cell-cycle arrest." (PMID 30972427, 2019). "Among them, β-elemene enhanced cisplatin activity by causing lung cancer cell death, which was regulated by the CHK2-mediated cdc25C/cdc2/cyclin B1 signaling pathway to block cell cycle progression at G2/M phase." (PMID 30609771, 2019). "Ectopic overexpression of TTP suppressed CCNB1 expression but depletion of TTP promoted the accumulation of CCNB1 mRNA in human lung cancer cells." (PMID 30380668, 2018). "We found that GPx3 overexpression significantly reduced nuclear translocation of NF-κB upon oxidative stress, thereby inhibiting cyclin B1 expression in lung cancer cells." (PMID 30260967, 2018). "We also found that inactivation of cyclin B1 significantly suppressed by nuclear factor-κB(NF-κB) inactivation in lung cancer cells was dependent on GPx3 expression." (PMID 30260967, 2018). "Among them, four genes involved in the GADD45 signaling pathway (CCNE2, CCND3, CDKN1A, and CCNB1), were reactivated by promoter DNA methylation in the GA-treated lung cancer H1299 cells." (PMID 29416619, 2018). "In the present study, DDA1 was shown to be responsible for lung cancer cell G1/S transition and cell proliferation through the regulation of cyclin D1, cyclin D3, cyclin E1 and cyclin B1 expression." (PMID 28211159, 2017). "Axl can regulate the expression of miR-374a and miR-548b and target Wnt5a and cyclin B1 (CCNB1) in gefitinib-resistant lung cancer cells." (PMID 27999207, 2017). "The results showed that of all the mRNAs, expression of cyclin B1 was positively correlated with levels of lncRNA16 in 20 lung cancer tissues and adjacent matched normal tissues." (PMID 27999202, 2017). "Among the tumor types evaluated, elevated expression of cyclin B1 in tumor tissues was related with worse 3- and 5-year OS of lung cancer and esophageal carcinoma." (PMID 27903976, 2017). "cyclin B1 overexpression was correlated with worse 5-year OS of lung cancer (OR = 2.60, 95% CI = 1.47 to 4.60, P = 0.0010) and esophageal cancer (OR = 5.17, 95% CI = 2.83 to 9.44, P < 0.00001)." (PMID 27903976, 2017).
lung cancer (continued). "Knockdown of Sox2OT expression suppressed cancer cell growth by inducing G2/M arrest, prohibiting S phase entry and inhibiting cell proliferation which correlated with reduced protein levels of Cdc2 and Cyclin B1 in human lung cancer cell lines." (PMID 28489861, 2017). "Real-time PCR and Western blot analysis revealed that silencing PLPP4 repressed the mRNA and protein expression levels of critical cell cycle regulators of the G1/S checkpoint CCND1, CCNA2 and CCNB1 in lung carcinoma cells." (PMID 28851360, 2017). "FSTL1 inhibition induced the cellular portion of G2/M phase in human lung cancer cells via the accumulation of regulators of the transition through the G2/M phase, including the cyclin-dependent kinase 1 (Cdk1)-cyclin B1 complex." (PMID 26716515, 2016). "In this study, we showed that 6-OAP inactivated NIPA and accumulated Cyclin B1 in lung cancer cells." (PMID 26474281, 2015). "In conclusion, the present study revealed that CuB inhibited proliferation in lung cancer cells, with cell cycle inhibition and cyclin B1 downregulation." (PMID 25242136, 2014). "The present study also demonstrated that CuB dose-dependently inhibited lung cancer cell proliferation, with cell cycle inhibition and cyclin B1 downregulation." (PMID 25242136, 2014). "For example, loss of caveolin 1 expression and overexpression of cyclin B1 in lung cancer tissue have previously been reported in studies with cDNA arrays and immunohistochemical analyses." (PMID 22348039, 2012). "AAbs to cyclin B1 in patients with breast and colon carcinoma were primarily of the IgG isotype whereas patients with pancreatic and lung carcinoma had in addition AAbs of the IgA isotype." (PMID 21113302, 2010). "LicoA induces G2/M-phase cell cycle transition by decreasing the expression of MDM2, cyclin B1, cdc2, and cdc25c proteins, and it causes apoptosis by upregulating the activation of proapoptotic caspase-3 and PARP cleavage via ER stress in human lung cancer." (PMID 40002335, 2025). "Besides, 3-DSC caused cell cycle arrest in colon and lung cancer cells by reducing the expression of CDC2, p27, and CCNB1." (PMID 39318781, 2024). "Romidepsin and SAHA increased histone and tubulin acetylation, downregulated the expression of cdc2 and cyclin B1, reduced the level of phosphorylated Rb (p-Rb), and increased p21 expression, and these changes led to G2/M arrest in breast and lung cancer cell lines." (PMID 37628767, 2023). "Cyclin B1 (CCNB1) was reported to be overexpressed in many cancers such as lung cancer." (PMID 36287252, 2023). "Here we demonstrated that the enriched lactate promotes transcriptional activation of cell cycle-related gene CCNB1 by histone lactylation (H4K12la) in lung cancer brain metastatic cells, supporting that histone lactylation also plays an important role in the acquirement of chemoresistance." (PMID 37587486, 2023). "Lung cancer patients’ prognoses are often foreseen using matched prognostic models, and genes CENPF, AURKA, PBK, and CCNB1 in lung cancer may serve as therapeutic targets, which require further investigations." (PMID 36984548, 2023). "This study shows that lung cancer patients with high expression of CCNB1 mRNA may have a poor prognosis, which can be used as an independent risk factor for poor prognosis in patients with lung squamous cell carcinoma." (PMID 36714024, 2023). "Additionally, the survival analysis demonstrated the consistent oncogenic role of CCNB1 in lung cancer." (PMID 34359836, 2021). "Here we present evidence to show that expression levels of BRG1, a chromatin remodeling protein, are elevated in human lung cancers as they become more aggressive paralleling the up-regulation of genes involved in cell proliferation (CCNB1) and migration (LTBP2)." (PMID 31695026, 2019).
lung cancer (continued). "We overexpressed or silenced CCDC106 to investigate its influence on lung cancer cell cycle regulators, including Cyclins A2, B1, D1, D2, D3, E1, E2, and H. Cyclin A2 and Cyclin B1 protein levels increased following CCDC106 overexpression, and decreased following CCDC106 knockdown." (PMID 28460455, 2017). "Cyclin B1 and cyclin D1 are usually over-expressed in lung cancer cells." (PMID 23739680, 2013). "Also, a contemporary study has determined that the levels of anti-CCNB1 antibodies increase with histological grades and stages of cancer, supporting the importance of early-stage screening and recurrence follow-up in advanced stages of lung cancer." (PMID 32752229, 2020). "In this study, we showed that CIP2A functions as an oncogene in lung cancer that upregulated the c‐MYC and Cyclin B1." (PMID 41362702, 2025). "It was also found that RING1 KD promotes lung cancer cell proliferation by upregulating CIP2A expression followed by increase of c‐MYC, and Cyclin B1." (PMID 41362702, 2025). "Collectively, higher CIP2A expression followed by RING1 reduction in lung cancer cells increases cell proliferation by c‐MYC and Cyclin B1 upregulation through inhibition of PP2A activity." (PMID 41362702, 2025). "In lung cancer cells, CUDC-907 initiated G2/M phase arrest through reducing the expression of cell cycle regulatory proteins as Cdc25C, CdC2, and Cyclin B1, and by elevating p21 protein level." (PMID 41148814, 2025). "GEPIA online software was used to analyze the expression of CHEK1, CCNB1, CCNB2, and CDK1 in 969 lung cancer tissues (including lung adenocarcinoma and lung squamous cell carcinoma) and 685 normal lung tissues." (PMID 36714024, 2023). "Combined with the results of this study, it can be inferred that CHEK1, CCNB1, CCNB2, and CDK1 are critical genes involved in cell cycle arrest and DNA damage repair in lung cancer." (PMID 36714024, 2023). "CHEK1, CCNB1, CCNB2, and CDK1 are the critical core genes of lung cancer and are highly expressed in lung cancer." (PMID 36714024, 2023). "The expression of CHEK1, CCNB1, CCNB2, and CDC2 was negatively correlated with the prognosis of patients with lung cancer (P < 0.01)." (PMID 36714024, 2023). "Kaplan–Meier plotter was used to analyze the prognosis of the core genes CHEK1, CCNB1, CCNB2, and CDK1 in patients with lung cancer." (PMID 36714024, 2023). "The microarray datasets GSE7670, GSE151102, GSE33532, GSE43458, and GSE19804 were further analyzed to determine the accuracy and reliability of the related expression of the four essential core genes (CHEK1, CCNB1, CCNB2, and CDK1) in lung cancer." (PMID 36714024, 2023). "Depletion or inhibition of BRG1 downregulated cyclin B1 (CCNB1) and latent TGF-β -binding protein 2 (LTBP2) in lung cancer cells." (PMID 36420141, 2022). "We have previously shown that Anthos favorably modulate targets such as β-catenin, cyclin D1, cyclin B1, pERK, VEGF proteins, c-myc and MMP9 in lung cancer H1299 cells." (PMID 34926717, 2021). "BRG1 is pivotal for the expression of cyclin B1 and latent TGF binding protein 2 (LTBP2), the upregulation of which is correlated with malignant lung cancer growth." (PMID 32354028, 2020). "In brief, we found that the USP7 was highly expressed concomitantly with the mitotic factors such as PLK1, CCNB1, CDC25A, and AURKB in prostate and lung cancer." (PMID 33207738, 2020). "In this study, we obtained eight lung cancer-related genes (CDC25C, TWIST1, HIF1A, DNMT1, PARP1, CDKN1A, CCNB1, and BIRC5) as seed nodes, using an RWR algorithm analysis to prioritize lung cancer related genes." (PMID 33193600, 2020).